CCNB1 (cyclin B1)
Diseases named in the same sentence as CCNB1 in open-access papers (continued):
Sharing a sentence is not in itself a finding about the gene and the disease.
tumor (continued). "Cyclin B1/CDK1 complex mediate mitochondrial activities in cell cycle progression and stress response as well as metabolism energy reprogramming in tumor adaptive resistance." (PMID 33339392, 2020). "We found that the protein of TTK, CCNB1, and CCNB2 much stronger expressed in tumor cells and immune cells in NSCLC when compared with that in normal lung tissues." (PMID 32969465, 2020). "DEmRNAs, including ATAD2, KIF23, MCM4, CCNB1, and CCNE1, are highly expressed in LUAD than in corresponding non-tumor tissues." (PMID 33042838, 2020). "Cytoplasmic and nuclear stain of CCNB1 (n = 246,642 samples) and PTTG1 (n = 243,624 samples) were observed in a low fraction of the tumor cells." (PMID 31801961, 2020). "Since the cyclin B1/cdc2 kinase plays a vital role as M-phase promoting factor in the G2/M transition, our results suggested that the SOV anti-tumor mechanisms have a close relationship with G2/M arrest." (PMID 32940655, 2020). "In analysis of multiple tumor areas, prognostic value was observed for cytoplasmic BUB3, CCNB1, and PTTG1." (PMID 31801961, 2020). "The expression of BUB3, CCNB1, and PTTG1 has been shown to correlate with tumor grade and prognosis in some cancers." (PMID 31801961, 2020). "In order to carry on the anti-tumor treatment, medicines inhibited the function of MPF through targeting CCNB1 to prevent cell mitosis." (PMID 31134129, 2019). "Cell cycling proteins CDK4 and cyclin B1 were also reduced, as were markers for epithelial–mesenchymal transition (EMT) and fibronectin in both tumor types but vimentin was reduced in tumors induced by B16-F10." (PMID 31615091, 2019). "In conclusion, we demonstrated that miR-144, serving as tumor suppressor, played an inhibit role in the occurrence and development of HCC by negative regulation of CCNB1 expression, thereby contributing to the progress of HCC." (PMID 30651720, 2019). "The oncogenic activity of hnRNPR was dependent on its ability to stabilize the mRNA of CCNB1 and CENPF, which are key mediators of cell cycle and tumor metastasis, respectively." (PMID 31527303, 2019). "A critical finding is that miR-9, as a tumor-suppressive microRNA, operated through the IGF1R pathway to regulate the targeting of cyclin B1 and N-cadherin and the upregulation of E-cadherin in CRC cells in the HG-concentration medium." (PMID 30965609, 2019). "Consistent with the expression results analyzed by ONCOMINE, the expression levels of CDK1, CCNB1, CCNB2, MAD2L1, and TOP2A assessed by TCGA data were all upregulated in tumor tissues compared with the normal controls (all P < 0.05)." (PMID 31886163, 2019). "Upregulated BUB1B, CCNB1, CDC7, CDC20, and MCM3 in HCC tumor tissues also contributed to worse DFS in HCC patients (Log rank P = 0.000052, 0.0192, 0.0307, 0.00496, and 0.0284, respectively)." (PMID 30363964, 2018). "Specifically, multiple cancers exhibit gene down regulation involving CCNB1 and BUB1, highlighting the relationship between a disrupted spindle assembly checkpoint and tumour formation." (PMID 29618387, 2018). "The boxplots showed that the expression levels of CCNB1, CCNB2, and CHEK1 were significantly higher in primary tumor than those in the normal liver for LIHC patients from TCGA (p<0.001)." (PMID 30228980, 2018). "BUB1B, CCNB1, CDC7, CDC20, and MCM3 were significantly increased in HCC patients with neoplasm histologic grade G3-4 compared to those with G1-2 (all P < 0.05)." (PMID 30363964, 2018). "BUB1B, CCNB1, CDC7, CDC20, and MCM3 were all overexpressed in HCC patients with neoplasm histologic grade G3-4 compared to those with G1-2 (all P < 0.05)." (PMID 30363964, 2018).
tumor (continued). "The anti-tumor effect of dinaciclib is likely mediated through cell cycle inhibition and apoptosis induction given that CKD1, cyclin B1, Aurora A, Mcl-1, Bcl-xL, survivin and pro-caspase-3 levels were all decreased." (PMID 28207834, 2017). "The present analysis showed, for the first time, that the anti-tumor effect of fisetin was mediated mainly through activation of CDKN1A, SEMA3E, GADD45B and GADD45A and down-regulation of TOP2A, KIF20A, CCNB2 and CCNB1 genes." (PMID 28052097, 2017). "As expected, we found that gene expression patterns are different in PC tumor samples compared to normal, undiseased peritoneum with a number of genes differentially regulated: BAG1, CCNB1, CD44, CLDN4 and 6, MMP2, MKI67, MUC1, MYBL2, and SERPINB3." (PMID 27542596, 2016). "miR-154, miR-379, and miR-300 have been shown to be decreased in different types of cancer cells, and they function as tumor suppressors by targeting TLR2, Cyclin B1, and Twist, respectively." (PMID 27070142, 2016). "Consistently, in FBXO22 overexpressed tumor tissues, the expression levels of p21Cip1/WAF1, and Cyclin B1 were also affected." (PMID 26087183, 2015). "Taken together, these data suggest a potential role for cyclin B1 and BIRC5 in PTTG1-mediated tumour growth." (PMID 26445238, 2015). "In CE81T tumor-bearing mice, 1BB1 reduced tumor growth and downregulated TGF-β, cyclin B1, MMP-1, and CXCR4 expression in tumors." (PMID 24130695, 2013). "We observed a striking decrease in the levels of PCNA, cyclin B1 and CDK4 levels and increase in the levels of tumor suppressor E-cadherin and pro-apoptotic protein Bim in the tumor tissue lysates of RLIP76 antisense-treated mice as compared with controls." (PMID 22509328, 2012). "Unsupervised hierarchical cluster based on relative quantification of the 5 E2F-induced genes, CCNA2, CCNB1, CCNB2, MSH6 and MCM7, by RT–qPCR divided the 24 tumours into two groups." (PMID 22045185, 2011). "The expression of SERPINA, TFF1, CCNB1 and CDC2 were also measured by qRT-PCR in 42 of the tumour samples assayed by microarray." (PMID 20646288, 2010). "An example of this is cyclin B1, where the gene expression was up-regulated in 9/12 cases (75%) and the mRNA levels tended to be high in grade III tumours." (PMID 19615042, 2009). "Consistent with the immunohistochemistry in other studies, several cell cycle regulators (e.g., CDKN2A (p16), CCNA2, CCNB1, CCNE2) were expressed at significantly higher levels in the tumor epithelium of African-Americans than European-Americans." (PMID 19225562, 2009). "Tumor cell survival and progression was determined by clonogenic analysis, flow cytometry, EMSA analysis of NF-κB, and western blot analysis of cyclin B1, p21WAF1/Cip1, and cleaved PARP protein." (PMID 16640785, 2006). "Additionally, we uncovered that SNRPB enhanced CCNB1 expression through FOXM1-mediated transcriptional activation, contributing to tumor growth." (PMID 40682115, 2025). "To explore the cellular role of CCNB1 in CRC, we analyzed scRNA-seq data from a tumor sample." (PMID 41614789, 2025). "For instance, it was found that hsa-mir-142 dominates the gene-miRNA-tumor purity correlation, PCNA dominates both the gene-protein-tumor purity correlation and the miRNA-protein-tumor purity correlation, and CCNB1 dominates the miRNA-protein-tumor purity correlation." (PMID 40228208, 2025). "By integrating bioinformatics analyses, IHC staining of patient tissues, and in vitro functional studies, we demonstrated that PLCH1 promoted tumor cell proliferation and survival by regulating cell cycle proteins (CDK1 and Cyclin B1) and the ERK-EGR1 signaling pathway." (PMID 40519297, 2025).
tumor (continued). "While CCNB1 and CHEK1 showed decreased eigenvector centrality in metastasis, CHEK1 plays a key role in the DNA damage response and contributes to tumor progression and therapy resistance in PCa, particularly in metastatic castration-resistant prostate cancer (CRPC)." (PMID 40626556, 2025). "Survival analysis revealed that increased CCNB1 expression and advanced cancer stage were associated with poorer overall survival, whereas no significant impact of CDC20 expression or tumor grade on survival was observed." (PMID 39795587, 2024). "Moreover, the dysregulation of cell-cycle-regulated genes (PLK1, CCNB1, CDKN2A, CCNE2, E2F1, and E2F2) by miR-5100 consistently resulted in upregulation in tumor tissues." (PMID 39590378, 2024). "This analysis revealed significant differences in the median expression levels of CCNB1 between most human tumor tissues and their corresponding normal tissues, particularly in the lung, blood, brain, breast, digestive organs, reproductive system, and colon." (PMID 38581717, 2024). "Silencing CDCA8 could suppresses tumor growth, proliferation, and stemness of HCC by inactivating AKT/β–Catenin Signaling, and regulating the CDK1/cyclin B1 signaling axis." (PMID 38742112, 2024). "Conversely, downregulation of CCNB1, which reduces CDK1/CCNB1 activity, could inhibit the aggressive proliferation of tumor cells." (PMID 39795587, 2024). "In addition, WDR4 activates the transcription of tumor promoting gene MYC, and promotes the binding of EIF2A and Cyclin B1 (CCNB1) mRNA to enhance the translation of CCNB1, thus promoting the development of HCC." (PMID 39850560, 2024). "In the present study, the analysis did not reveal a statistically significant difference in CCNB1 gene expression fold-change between the different tumor grade groups." (PMID 39795587, 2024). "Moreover, the protein levels of PLK‐1, CCNB1, CCNB2, and SIRT2 were observed to decrease in a dose‐dependent manner in tumor tissues following treatment with VS‐5584 in comparison to the control group." (PMID 37658623, 2023). "Among them CCNB1, MIF, PLA2G4A may be regarded as oncogenes, whereas RNASE3, APOE, FOXO1, KIT, and EGR1 may be tumor suppressor genes." (PMID 37065484, 2023). "In the METABRIC cohort, multivariate Cox regression analysis showed that CCNB1 mRNA predicted poor BCSS survival independent of tumour size, LN stage, tumour grade and LVI (HR 1.5; 95% CI 1.2–1.8; p < 0.0001)." (PMID 36418517, 2023). "Western blot results showed that S1PR1, cyclin B1, PDK1, and lamin B1 protein levels were significantly decreased, whereas P21, P62, histone H3, IGFBP7, and PAI-1 protein levels were significantly increased in S1PR1 knockout tumor tissue." (PMID 37828220, 2023). "hnRNPR stabilizes CCNB1 and CENPF mRNA to promote tumor metastasis." (PMID 37479693, 2023). "CCNB1 and CDK1 are key cell cycle molecules that can affect tumor growth and metastasis." (PMID 37994323, 2023). "who could show that ZIC5 is highly upregulated in NSCLC tumor tissues, and they suggested that ZIC5 may act as an oncogene by influencing CCNB1 and CDK1 complex expression." (PMID 37228492, 2023). "Furthermore, Bas featured a diffuse, full-thickness, unpolarized proliferation activity, unlike urothelial-like tumors, as demonstrated by staining for CCNB1 and KI67 throughout the tumor parenchyma." (PMID 35887192, 2022). "In addition, we also used GEPIA2 to investigate the expression of CCNB1 and PLK1 in a variety of other cancers, and the results demonstrated that they were highly expressed in most tumor tissues." (PMID 35456460, 2022). "Overall, CCNB1, CDK1, and PAICS could be three critical genes that influence tumor stage development of NSCLC and they could produce a poor prognosis." (PMID 36081668, 2022). "Furthermore, by performing IHC staining using mouse tumor tissues, we found that SR9009 treatment reduced the expression of FOXM1 and its target genes CCNB1, CCNB2 and Survivin." (PMID 36357378, 2022).
tumor (continued). "In addition, CDK1, CCNB1, and KIAA0101 were found to be substantially overexpressed in CCA, which can promote the proliferation of tumor cells." (PMID 36224755, 2022). "The compound may also suppress the expression of cyclin B1 and CDK1 in BC cells, resulting in apoptosis and inhibition of tumor cell growth." (PMID 34439842, 2021). "The qRT-PCR results showed that CCNB1, CDK1, and RRM2 were significantly upregulated in liver cancer tumor samples (P < 0.0001) and cell lines (P < 0.05) compared with the relevant adjacent non-tumor liver tissues and normal liver cell LO2." (PMID 33685467, 2021). "Based on downstream analysis, 5 hub genes, including CDK1, CDC20, CCNB1, CENPF, and MAD2L1, that could play a critical role in the early diagnosis, tumour stage, and poor outcomes of HBV-HCC were identified." (PMID 34603487, 2021). "CCNA2, CCNB1, and CCNE1 were co-expressed with BIRC5, a well-known cancer therapeutic target which directly regulates both apoptosis and mitosis in cancer cells during tumorigenesis and tumor metastasis." (PMID 33996604, 2021). "The novelty of our work is that we firstly address the correlation between CCNB1, EZH2, and tumor immune microenvironment in docetaxel resistant PCa, and further investigate the relationship between immune cell infiltration and the expression of these two prognostic hub genes." (PMID 34077304, 2021). "In this study, the differential expression analysis showed that among all cyclin family members, there were six significant DEGs (CCNA2, CCNB1, CCND1, CCNE1, CCNF, and CCNJL), five of which were overexpressed in tumor samples compared to normal controls, while CCNJL was downregulated." (PMID 33996604, 2021). "In addition, the expression of the cell proliferation markers AURKA, AURKB, CCNB1, and MKI67 was higher in the patients’ tumor tissues than those of normal tissues." (PMID 34503223, 2021). "Much attention is currently given to the proliferation-related mechanism of BC due to the functional specificity of BIRC5/survivin in activating Aurora B kinase within the chromosomal passenger complex, and its co-localization with other tumor proliferation genes MKI67, CCNB1, and AURKA." (PMID 34064473, 2021). "Hence, the expression of CCNB1, CDC25C, and CHEK2 played an important role in the carcinogenicity and tumor progression of NSCLC." (PMID 34504528, 2021). "Based on the results of functional analyses, we firstly hypothesized that CCNB1 and EZH2 could be involved in chemoresistance through changing the tumor immune microenvironment." (PMID 34077304, 2021). "Through analysis of DEG expression in the TCGA database, CCNB1 expression was conspicuously high in tumor samples more than nontumor samples (log FC = 1.53, p = 1.25E-39)." (PMID 33628185, 2020). "Functional studies further demonstrated that stable short hairpin RNA (shRNA)-mediated knockdown of MGLL inhibits tumor proliferation and metastasis, both in vitro and in vivo, and mechanistically, our data indicate that MGLL regulates Cyclin D1 and Cyclin B1 in LUAD cells." (PMID 33363004, 2020). "Indeed, Cyclin-D, Cyclin-B1 and TOMM20 play a fundamental role in the progression of the tumor cell cycle." (PMID 33339392, 2020). "High expression of CCNB1 was also observed in BRCA1-mutant cancer and induction of vinblastine targeting CCNB1 could significantly reduce tumor progression." (PMID 32716025, 2020). "Overexpression of CDC25C may be related to the activation of the cyclin B1/CDK1 complex and promote the growth of the corresponding tumor, and there is a correlation between survival and proliferation rate." (PMID 32518522, 2020).
tumor (continued). "Moreover, TNF-α, IL-6, and several typical differentially expressed phosphorylated proteins (such as p-CCNB1, p-FOXO3, and p-STAT3) in tumor tissues, tumor cell viability, and cell cycle arrest assay in vitro further verify the results of IPA." (PMID 33344655, 2020). "MP-HX downregulated the expression of genes that could promote anti-apoptotic effect, cell cycle progression, tumor development and progression, which include BIRC5, CCNA2, CCNB1, CCNB2, CCNE2, CDK1/2/6, GINS2, HELLS, MCM2/10 PLK1, RRM2 and SKP2." (PMID 30042885, 2018). "This means that when the expression level of CCNB1, CDC25C, CDK1 and PLK1 is reduced, the abilities in tumor cells proliferation could be inhibited at the same time." (PMID 29500418, 2018). "When the mice had a tumor size of 100 mm3, they were treated with 0.1 mL of PBS (as a control), free cyclin-B1 siRNA (100 μg), control siRNA Cyc-B3(50 μg), cyclin-B1-siRNA (5 μg and 10 μg) complexes with MPG-8/chol-MPG-8 at a 1/20 molar ratio and cyclin-B1 siRNA with MPG-8(10 μg) in every 3 days." (PMID 29861465, 2018). "Western-blot analyses of the tumor tissue lysates from 2HF treated mice revealed reduction in cell growth promoting signals such as AKT and p70S6K, proliferation signals such as CDK4 and cyclin B1." (PMID 30546837, 2018). "When the mice had a tumor volume of 50 mm3, the mice were treated with glucose (as a control), negative control ssiRNA and cyclin-B1-ssiRNA at a dose of 1 mg/kg intravenously every alternative day." (PMID 29861465, 2018). "Western blot analysis of lysates of tumor tissue showed that selinexor decreased the protein levels of XPO1 and cyclin B1 and increased the levels of p21 and cleaved caspase 3 in the mice receiving selinexor compared with tumors in mice treated with vehicle control." (PMID 27893412, 2017). "The Western blot analyses of 2HF treated tumor tissue lysates, as compared with untreated controls, revealed a decrease in the level of proliferation proteins pAKT, survivin, RLIP76, pERK, pJAK2, STAT3, CDK4 and cyclin B1." (PMID 29088842, 2017). "Interestingly, many of these genes are known to be involved in cell-cycle function (CDK2, CDK6, CCNB1, CEP55, CENPF), transcriptional regulation/tumor suppression (FOXO3, TOP2A), DNA-damage response (ASPM, XRCC4), and tumor progression (CYR61, MACC1, CXCR4)." (PMID 28482906, 2017). "One of the potential mechanisms that underline the DNMT3B-mediated arrest involves the ability of DNMT3B siRNA to reduce the expression of different cyclins (Cyclin B1, Cyclin D1 and Cyclin E2) and to block the pRB/E2F1 pathway by inducing de-phosphorylation of RB tumour suppressor." (PMID 27764816, 2016). "In combination with the increased ROS levels generated by hyperthermia, this might be the reason for the more significant decrease of Cyclin B1 and CDK1 in tumours co-treated with hyperthermia and 17-DMAG." (PMID 27909289, 2016). "Besides, different from CCNB1, CCNA1 functions in S and G2/M phases, which is due to its two different phosphorylated substrates, CDK1 and CDK2, subsequently conducing tumor cells proliferation." (PMID 26999101, 2016). "Downregulation of cyclin B1 might be responsible for mitotic arrest and inhibition of tumor growth by the PEM in the tumor-bearing mice." (PMID 25983747, 2015). "According to the maximal Youden index, the optimal cut-off value for Cyclin B1 expression was 3.33 fold in tumor/non-tumor." (PMID 25962181, 2015).